SLC2A13 (solute carrier family 2 member 13)
Description:
H(+)-myo-inositol cotransporter. Can also transport related stereoisomers.
Synonyms: Hmit
Tractability: Antibody: UniProt places it where antibodies can reach, with high confidence; its Gene Ontology location is reachable by antibodies, with high confidence; UniProt predicts a signal peptide or a membrane-spanning region. PROTAC: ubiquitination databases record sites on it; its protein half-life has been measured.
Gene: Protein-coding gene on chromosome 12 (39,755,025 to 40,106,089, reverse strand). Ensembl gene ENSG00000151229.
Subcellular location: Cell membrane
Subcellular location (Human Protein Atlas): Nuclear membrane
Pathways (Reactome):
Transport of small molecules: Inositol transporters
Gene Ontology:
Molecular function: ATPase binding; myo-inositol:proton symporter activity; protease binding; protein binding; myo-inositol transmembrane transporter activity; transmembrane transporter activity
Biological process: myo-inositol transport; positive regulation of amyloid-beta formation; transmembrane transport; transport across blood-brain barrier
Cellular component: cell body; cell periphery; cell projection; plasma membrane; apical plasma membrane; astrocyte end-foot; cytoplasm; early endosome; Golgi apparatus; growth cone; lysosome; membrane; organelle membrane; synaptic vesicle
Genetic constraint (gnomAD): Loss-of-function variants: 32 observed, 58.5 expected, observed/expected ratio (o/e) 0.55, 90% interval 0.41 to 0.74. The upper end of that interval is the gene's LOEUF score, 0.74, which puts it in group 3 of 6, group 1 being the genes least tolerant of losing a copy. Missense variants: 741 observed, 767.08 expected, observed/expected ratio (o/e) 0.97, 90% interval 0.91 to 1.03. Synonymous variants: 338 observed, 292.41 expected, observed/expected ratio (o/e) 1.16, 90% interval 1.06 to 1.26.
Homologues: Orthologues: chimpanzee SLC2A13 (99% identical), macaque SLC2A13 (99% identical), pig SLC2A13 (97% identical), dog SLC2A13 (96% identical), rat Slc2a13 (90% identical), mouse Slc2a13 (88% identical), tropical clawed frog slc2a13 (82% identical), guinea pig SLC2A13 (76% identical), zebrafish slc2a13b (63% identical), rabbit SLC2A13 (63% identical), Caenorhabditis elegans hmit-1.3 (38% identical), zebrafish SLC2A13 (37% identical), and 33 more. Paralogues in human: SLC2A12 (25% identical), SLC2A4 (23% identical), SLC2A2 (23% identical), SLC2A5 (22% identical), SLC2A14 (22% identical), SLC2A3 (22% identical), SLC2A8 (22% identical), SLC2A1 (22% identical), SLC2A10 (21% identical), SLC2A7 (21% identical), SLC2A9 (20% identical), SLC2A6 (19% identical), and 1 more.
Diseases named in the same sentence as SLC2A13 in open-access papers:
SLC2A13 is named in the same sentence as 18 diseases in open-access papers, as found by Europe PMC text mining. Sharing a sentence is not in itself a finding about the gene and the disease. The quoted sentences say what the papers report.
diabetes (2 papers, 2019). "At E10.5, effects of diabetes were significant for Slc27a6/Fatp6, Slc27a4/Fatp4, and Cpt2 (27.8%, 19.4%, and 19.7%, respectively), and for Cpt1a, Slc2a13/Glut13, and Cpt1b, diet was a significant contributor (42.9%, 38.7%, and 31%, respectively)." (PMID 31774824, 2019). "Alterations of expression levels by diet were observed for all Slc2as/Gluts; greater than two-fold were only observed for Slc2a3/Glut3 at E12.5, for Slc2a6/Glut6 at E9.5 and E18.5, for Slc2a8/Glut8 at E9.5, E12.5 and E18.5, and for Slc2a13/Glut13 at E9.5, regardless of diabetes exposure." (PMID 31774824, 2019).
breast adenocarcinoma (1 paper, 2023). "It was also found that SLC2A13 expression was induced in human breast adenocarcinoma MCF7 cells after serum starvation, making it a potential marker for various cancer stem cells." (PMID 37664112, 2023).
breast tumors (1 paper, 2023). "Specifically, SLC2A1, SLC2A6, SLC2A10, and SLC2A13 were significantly overexpressed, whereas SLC2A3, SLC2A4, SLC2A9, SLC2A11, and SLC2A12 had downregulated expressions in breast tumors compared with those in normal breast epithelium." (PMID 37108300, 2023).
Crohn disease (1 paper, 2023). A gastrointestinal disorder characterized by chronic inflammation involving all layers of the intestinal wall, noncaseating granulomas affecting the intestinal wall and regional lymph nodes, and transmural fibrosis. "The two trait pairs however differed in their strongest association, which was in the SLC2A13 locus on chromosome 12 (shared with LRRK2) for Parkinson’s disease-Crohn’s disease but in the ‘MHC’ locus on chromosome 6 for Parkinson’s disease-UC." (PMID 36687396, 2023).
depression (1 paper, 2023). "For depression without suicide, the MPOL1 and SLC2A13 gene had the highest Gini index score and may be the candidate molecules." (PMID 36781900, 2023).
frontotemporal dementia (1 paper, 2021). Frontotemporal dementia (FTD) comprises a group of neurodegenerative disorders, characterized by progressive changes in behavior, executive dysfunction and language impairment, as a result of degeneration of the medial prefrontal and frontoinsular cortices. "Another important potential target was the inhibition of the Solute Carrier Family 2 (Facilitated Glucose Transporter) Member 13 protein encoded by Slc2a13, recently identified a risk factor in frontotemporal dementia." (PMID 33968923, 2021).
nicotine dependence (1 paper, 2025). Physical and psychological dependence on nicotine. "Previous reports indicated that SLC2A13, BHLHE41, VGF and AHR variants are associated with heavy and problem drinking in patients as well as with nicotine dependence in tobacco users." (PMID 39880903, 2025).
oral squamous cell carcinoma (1 paper, 2013). "Lee and coworkers have established H+-myo-inositol transporter SLC2A13 as a potential biomarker for cancer stem cell (CSC) in oral squamous cell carcinoma (OSCC)." (PMID 23586059, 2013).
cancer (4 papers, 2013 to 2024). A tumor composed of atypical neoplastic, often pleomorphic cells that invade other tissues. "On the other hand, some genes’ function such as SNX22 and SLC2A13 were scarcely reported in cancer." (PMID 39538125, 2024).
SLC2A13 also shares sentences with these, for which no sentence is quoted: Intellectual disability (2 papers); tumor (2); amyotrophic lateral sclerosis (1); colon cancer (1); developmental delay (1); lupus nephritis (1); Obesity (1); Parkinson disease (1); progressive supranuclear palsy (1).